BDNF (brain derived neurotrophic factor)
Diseases named in the same sentence as BDNF in open-access papers (continued):
Sharing a sentence is not in itself a finding about the gene and the disease.
Cognitive impairment (continued). "Previously, we have shown RZ-mediated restoration of brain BDNF levels and reversal of cognitive impairments in a chemotherapy-related brain injury model." (PMID 39696694, 2024). "We found a statistically significant positive correlation between the plasma BDNF levels and MoCA score (p = 0.04) in the subgroup of schizophrenic patients with a cognitive deficit (n = 29)." (PMID 37445746, 2023). "Conversely, hippocampus-specific deletion of the BDNF gene or local injection of anti-BDNF antibodies results in specific blockade of hippocampus-dependent functions, leading to memory and cognitive deficits." (PMID 36594063, 2023). "In human studies, acute serum BDNF levels are associated with chronic memory impairments, functional cognitive limitations, and depressive symptom severity, with an inverse correlation between BDNF levels and cognitive impairment." (PMID 36816569, 2023). "Previous studies suggested that GBE alleviates cognitive impairment in epileptic animals by increasing BDNF, neuropeptide Y or increasing the differentiation of neural stem cells." (PMID 36419341, 2023). "A recent study showed depression-like behaviors, cognitive impairment, and hippocampal BDNF downregulation in the offspring of mother mice that underwent sleep deprivation during pregnancy." (PMID 36983803, 2023). "BDNF levels in the central and peripheral nervous systems decrease with age, especially in older adults with mood disorders and cognitive impairment." (PMID 37009109, 2023). "An imbalance in gut microbiota can lead to reduced levels of BDNF in the hippocampus and cortical midbrain, potentially inducing cognitive impairment through the gut–brain axis." (PMID 38201846, 2023). "Enriched environment ameliorates postsurgery sleep deprivation‐induced cognitive impairments through BDNF/GluA1 pathway." (PMID 37095708, 2023). "The primary goal of this study is to look into the probable function of BDNF in diabetes-related cognitive impairment in both prediabetes and diabetes using mediator analysis." (PMID 36936159, 2023). "Our findings indicated that diet control and/or swimming exercise improved HFD-induced cognitive impairment through antineuroinflammation, which was associated with activating the SIRT1-NF-κB and SIRT1-PGC-1α-BDNF pathways." (PMID 36999158, 2023). "In this study, we carried out eight experiments using male mice to examine the causal involvement of the BDNF-TrkB pathway in dentate gyrus (DG) and the therapeutic effects of the TrkB agonist (7,8-DHF) in ELS-induced cognitive deficits." (PMID 37225683, 2023). "Several studies have indicated reduced BDNF and neurotrophin levels in the brains of patients diagnosed with AD and mild cognitive impairment (MCI)." (PMID 37190025, 2023). "Previous articles reported that the ERK/CREB/BDNF signaling pathway has a critical role in long-term synaptic plasticity in the hippocampus, particularly in diseases of cognitive impairment." (PMID 37271806, 2023). "Amelioration of cognitive impairment by up-regulating the CaMKIIα/CREB/BDNF pathway and EPO/EPOR pathways." (PMID 36875644, 2023). "Vatandoust and co-workers reported that sericin reduced cognitive impairment and enhanced BDNF expression in mice with learned helplessness disorder." (PMID 37936189, 2023). "The results indicate that increasing BDNF expression in the basal forebrain is important in combating sleep deprivation‐induced cognitive impairments." (PMID 37072935, 2023). "A meta-analysis reporting changes in BDNF through aerobic exercise showed improvements in BDNF levels in older adults with mild cognitive impairment (SMD = 0.48)." (PMID 37108444, 2023). "In the present study, we used CORT to induce depressive-like behavioral phenotypes and cognitive deficits in mice, which were accompanied by decreased BDNF levels in the DG, especially in neurons." (PMID 36793868, 2023). "Overexpression of PGC-1α induced hippocampal BDNF expression, leading to improved cognitive impairment." (PMID 36999158, 2023).
Cognitive impairment (continued). "Another study showed that high-frequency rTMS combined with cognitive training was effective in increasing serum BDNF concentrations in post-stroke cognitive impairment during stroke recovery." (PMID 37735708, 2023). "EGCG (2 g/day) upregulates IRS1/Akt and ERK/CREB/BDNF (brain-derived neurotrophic factor) signalling pathways, significantly decreasing IR and cognitive impairment in HFD and high-fructose-induced mouse models of cognitive impairment." (PMID 37036026, 2023). "The mediator role of BDNF in the relationship between diabetes and cognitive impairment was investigated by mediation analysis." (PMID 36936159, 2023). "Previous studies showed that CREB/BDNF pathway is responsible for the pathogenesis of cognitive impairment." (PMID 37140732, 2023). "Meta-analysis has shown that peripheral BDNF levels gradually decrease with increasing cognitive impairment and are only detectable in late-stage disease." (PMID 36979505, 2023). "In order to overcome the limitation of BDNF application, we developed and evaluated the therapeutic approach of irradiated BDNF-eMSCs in protecting the brain against neuronal death, neurological deficits, and cognitive impairment that arise following TBI." (PMID 36986535, 2023). "More importantly, our results of subchronic systemic administration of 7,8-DHF highlight the BDNF-TrkB pathway as the potential therapeutic targets for the treatment of cognitive deficits in stress-related psychiatric disorders." (PMID 37225683, 2023). "Aerobic exercise significantly increases the plasma levels of BDNF, nerve growth factor, motor activity, cognitive impairment, exploratory behavior, and spatial memory in people with AD." (PMID 37600508, 2023). "During cognitive impairment, it is common to see a decrease level of amyloid-β peptide and an increase level of BDNF." (PMID 38055394, 2023). "This, in combination with the established role of BDNF-Met in cognitive impairment in AD, clearly shows that there is a need for new treatments for AD that improve memory using a different mechanism of action than the anti-amyloid antibodies." (PMID 37446337, 2023). "Lactobacillus helveticus R0052e, Bifidobacterium longum R0175 attenuated cognitive defects, increased the expression of BDNF, and decreased the circulating and hippocampal levels of proinflammatory cytokines." (PMID 38248439, 2023). "Siuda and colleagues demonstrated a significant correlation between BDNF serum levels and cognitive impairment, where lower levels were observed in AD subjects." (PMID 36979505, 2023). "In limited studies on cognition and BDNF in T2DM patients, low BDNF levels were found to be associated with cognitive impairment and dementia." (PMID 36936159, 2023). "Dietary control and physical activity ameliorate HFD-induced cognitive impairment and abnormal neurometabolism, which is associated with SIRT1-mediated NF-κB pathways and PGC-1α-BDNF pathways." (PMID 36999158, 2023). "The resultsshowed that PAI-1 serum levels are increased in Alzheimer (23% more)and BDNF serum levels are decreased (13.7% less) as compared to amnesticmild cognitive impairment patients." (PMID 37810633, 2023). "This study was the first to examine the role of BDNF in cognitive impairment in T2DM and prediabetes using mediation analysis." (PMID 36936159, 2023). "Elderly patients with mild cognitive impairment showed a significant increase in BDNF concentration and improvement in executive function after intervention in the “memory channel” interactive cycling somatosensory game." (PMID 38038376, 2023). "GAP-43 and BDNF reduction in aged 5XFAD mice accelerates AD pathologies and triggers cognitive deficits." (PMID 37143467, 2023). "Relevant studies in the field have been conducted by Tuszynski and his colleagues, using lentivirus-expressing BDNF injected in the entorhinal cortex in both mice and primates which reversed atrophy and improved cognitive impairment." (PMID 37596686, 2023).
Cognitive impairment (continued). "EX has been identified as a potent and robust non-pharmacological intervention for enhancing cognitive function and limiting cognitive deficits through increased brain BDNF levels." (PMID 37868812, 2023). "Downregulating BDNF expression (conditional BDNF knockdown) or inhibition of the TrkB receptor (using its antagonist ANA-12) in the DG mimicked the cognitive deficits of ELS." (PMID 37225683, 2023). "Adolescent and young adult cancer patients were 3 times more likely to experience cognitive impairment prior to cancer treatment, and their BDNF levels were half of age-matched healthy controls." (PMID 36720792, 2023). "Strong stress induced by anesthesia and surgery accelerates nicotinamide adenine dinucleotide phosphate (NADPH) oxidase subtype NOX2 to induce microglia to release IL‐1β and downregulate BDNF, which is closely related to cognitive impairment." (PMID 38680509, 2023). "In contrast to the control group, another study demonstrated a significant increase in serum BDNF levels in individuals with cognitive impairment." (PMID 37009109, 2023). "In this study, the authors conclude that increased BDNF-mediated signaling is probably an adaptative process to counteract ethanol-induced cognitive deficits." (PMID 37509436, 2023). "(d) The mediating role of BDNF in the development of cognitive impairment in diabetes remains to be determined." (PMID 36936159, 2023). "Despite these limitations, the present study demonstrates BDNF-eMSCs’ efficacy in preventing neuronal death, neurological deficits, and cognitive impairment in a rodent model of TBI." (PMID 36986535, 2023). "The role of BDNF in the diabetes-related cognitive impairment was investigated through mediation analysis." (PMID 36936159, 2023). "Additional behavioral experiments are required to comprehensively evaluate the role of BDNF signaling in HI‐induced cognitive impairment." (PMID 37830170, 2023). "Post hoc analysis showedthat the PAI-1/BDNF ratio was significantly higher in the Alzheimergroup as compared to amnestic mild cognitive impairment (36.4% more)(p < 0.0001; 95% CI: −0.2, 0.097) and controls(40% more) (p < 0.0001; 95% CI: −0.25,−0.082)." (PMID 37810633, 2023). "These interventions also improve BDNF expression and insulin sensitivity and reduce cognitive disorders." (PMID 37600508, 2023). "We found the prognostic role of BDNF concentration and hemodynamic subtype in relation to cognitive impairment in the acute period of ischemic stroke." (PMID 36969561, 2023). "Spinosin has been reported to alleviate cognitive impairment by improving the neurotrophic factor (BDNF) and Bcl-2, decreasing the level of MDA, and inhibiting the inflammatory factor IL-6 in the brain." (PMID 36193419, 2022). "BDNF first decreased and then increased significantly with cognitive impairment in physical and technical occupation (P < 0.05), and BDNF increased gradually with cognitive impairment in intellectual occupation (P > 0.05)." (PMID 36425322, 2022). "The upregulation of miR-10b-5p results in the decrease of BDNF levels in mouse hippocampal neurogenesis and cognitive impairment model." (PMID 36163004, 2022). "BDNF overexpression alleviated motor deficits and cognitive impairment in MPTP-induced PD mice through mitigating mitochondrial damage." (PMID 36158555, 2022). "For recovering from chronic unpredictable stress‐induced cognitive deficits, curcumin effectively inhibited the reduction of hippocampal BDNF and ERK levels." (PMID 36251357, 2022). "The cognitive impairments are reported to be partly mediated by altered BDNF expression in the hippocampus." (PMID 36620458, 2022). "Consistent with our findings, supplementation of pomegranate-derived anthocyanins can improve the CREB/BDNF pathways and alleviate cognitive impairments in an opioid-dependent rat model." (PMID 35651724, 2022). "Another disease where the role of BDNF has been studied is schizophrenia, which is characterized by cognitive impairment." (PMID 35628626, 2022).
Cognitive impairment (continued). "In conclusion, the molecular mechanism of cognitive impairment in the elderly is related to the inhibition of AHN through the BDNF/TrkB and NT-3/TrkC pathways." (PMID 35309893, 2022). "Disruption of brain-derived neurotrophic factor (BDNF) and vascular endothelial-derived growth factor (VEGF) signaling in the aging brain was also associated with cognitive deficits." (PMID 36570840, 2022). "A recent study indicated that supplementation with eleutheroside E disturbs the microbiota, activating the PKA/CREB/BDNF signaling pathway, which in turn improves cognitive impairment in irradiated mice." (PMID 36499295, 2022). "Resveratrol reduced neurotoxin-induced cognitive impairment by regulating the hippocampal estrogen-N-methyl-D-aspartate receptor- (NMDAR-) brain-derived neurotrophic factor (BDNF) signaling pathway in female mice." (PMID 36425058, 2022). "For example, resveratrol (3, 5, 4’-trihydroxy-trans-stilbene) treatment ameliorates oxidative stress and cognitive deficits in a rat model of vascular dementia by increasing hippocampal BDNF expression." (PMID 35090576, 2022). "BDNF-loaded PLGA NPs display good penetration of BDNF resulting in improvement of neurological and cognitive deficits after TBI." (PMID 39872806, 2022). "BDNF first decreased and then increased significantly with the aggravation of cognitive impairment in groups aged 51–64 and 65–74 (P < 0.05), and BDNF increased gradually with cognitive impairment in the group over 75 years old (P < 0.05)." (PMID 36425322, 2022). "The result of this study suggests a novel hint in rescuing cognitive impairment by regulating the BDNF/proBDNF ratio." (PMID 35370607, 2022). "In this study, the levels of 5-HT, GABA, and BDNF in the blood of premature rats with cognitive impairment decreased, while that of GR, CRH, IL-6, and TNF-α increased, in comparison to the control group." (PMID 36061856, 2022). "More recent studies found that patients with schizophrenia with lower BDNF concentrations were characterized by lower processing speeds, cognitive impairment in visual learning and working memory domains, and executive function deficit." (PMID 35873262, 2022). "Our previous studies have shown that the lower level of the synaptic proteins, i.e., PSD95, SYP, and BDNF, is closely related to cognitive impairment." (PMID 36760797, 2022). "Taurine increases protein expression of BDNF and NGF, Significantly improved cognitive impairment caused by HBCDs in developing rats." (PMID 36187803, 2022). "Through a series of in vivo studies, we demonstrated that sevoflurane-induced cognitive impairment in aged mice depended on the inhibition of AHN in the SGZ through the BDNF/TrkB and NT-3/TrkC pathways." (PMID 35309893, 2022). "Here, we demonstrated that anesthesia/surgery induced a reduction of BDNF/proBDNF, which negatively regulates the synaptic function in hippocampus, subsequently leading to cognitive impairment in aged mice." (PMID 35370607, 2022). "BDNF is responsible for neuronal survival and synaptic plasticity, which helps in alleviating cognitive impairment." (PMID 35406030, 2022). "Such BDNF reductions were seen in the prefrontal cortex, also inversely correlating with cognitive impairments in more advanced AD patients, as well as in Tau-bearing and non-tangle-affected neurons in the frontal cortex of AD patients." (PMID 36117625, 2022). "This study revealed that a single session of simulated acute normobaric hypoxia leads to a significant impact on BDNF concentrations as well as cognitive impairment in the “naming” aspect of the Stroop test." (PMID 36078520, 2022). "Our results revealed that downregulation of P-NR2B and BDNF in the hippocampus of POCD mice was in synchrony with cognition impairment." (PMID 36212697, 2022). "Cognitive deficits induced by decreased BDNF levels can be alleviated by voluntary exercise and estrogen therapy, which regulate the expression of histone deacetylases." (PMID 35592114, 2022).